GBA1 (glucosylceramidase beta 1)
Diseases named in the same sentence as GBA1 in open-access papers (continued):
Sharing a sentence is not in itself a finding about the gene and the disease.
Gaucher disease (continued). "Gaucher Disease is the most common sphingolipidosis, caused by a mutation in the GBA1 gene, leading to impaired beta-glucocerebrosidase activity and glucosylceramide accumulation." (PMID 34201281, 2021). "Mutations in GBA1 lead to low or deficient levels of the GBA1 enzyme, also resulting in the development of the recessively inherited lysosomal storage disorder known as Gaucher Disease (GD)." (PMID 34884544, 2021). "Gaucher disease (GD), resulting from deficient lysosomal glucocerebrosidase, is caused by bi-allelic variants in GBA1 and is the most common genetic risk factor for the more common neurodegenerative disorder, Parkinson disease (PD)." (PMID 33920837, 2021). "Gaucher disease is an inherited metabolic storage disorder, which is caused by the mutations of GBA1, a gene encoding lysosomal enzyme β‐glucocerebrosidase." (PMID 33342090, 2021). "Homozygous mutations in GBA1 are responsible for Gaucher’s disease (GD), the most common lysosomal storage disorder." (PMID 33971917, 2021). "Gaucher disease (GD) is a rare, autosomal recessive genetic disease caused by mutations in the glucocerebrosidase (GBA1) gene, on chromosome 1 (1q21)." (PMID 34104165, 2021). "Mutations in the glucocerebrosidase (gba1) gene cause Gaucher disease (GD), the most common genetic risk factor for PD." (PMID 34550070, 2021). "Gaucher disease (GD) is a common lysosomal storage disorder usually associated with defective activity of the lysosomal glucocerebrosidase (encoded by GBA1, OMIM#606463)." (PMID 33530161, 2021). "This notion is supported by cases of mutations in the GBA1 gene, which encodes the lysosomal enzyme glucocerebrosidase (GCase) that is deficient in Gaucher’s disease (GD)." (PMID 34572087, 2021). "Gaucher disease (GD) is an autosomal recessive disorder caused by bi-allelic GBA1 mutations that reduce the activity of the lysosomal enzyme β-glucocerebrosidase (GCase)." (PMID 34576075, 2021). "Gaucher disease is caused by mutations in the GBA1 gene, which encodes a lysosomal enzyme, glucocerebrosidase (GCase); GBA1 mutations are a major risk factor for PD." (PMID 32392751, 2020). "Neurological forms of Gaucher disease, the inherited disorder of β-Glucosylceramidase caused by bi-allelic variants in GBA1, is a progressive disorder which lacks a disease-modifying therapy." (PMID 33334373, 2020). "Homozygous mutations in GBA1 cause an inherited lysosomal storage disease known as Gaucher disease (GD), while heterozygous mutations in GBA1 are the major known genetic risk factor for Parkinson’s disease (PD)." (PMID 31685979, 2020). "Gaucher disease (GD) is an inherited metabolic disorder caused by biallelic mutations in the GBA1 gene." (PMID 32967694, 2020). "Mutations in the GBA1 gene result in Gaucher disease and increased susceptibility to Parkinson’s disease." (PMID 32708198, 2020). "Gaucher Disease (GD), which is the most common lysosomal storage disorder, is caused by bi-allelic mutations in GBA1—a gene that encodes the lysosomal hydrolase β-glucocerebrosidase (GCase)." (PMID 33287247, 2020). "Mutations in one of these lysosomal genes, namely GBA1, result in Gaucher disease (GD), and mutations in GBA1 are now recognized as the highest genetic risk factor for Parkinson’s disease (PD)." (PMID 32674335, 2020). "Gaucher disease (GD), first described in 1882 by Dr. Phillipe Gaucher, is an inborn error of metabolism due to mutations in the gene GBA1, encoding the lysosomal enzyme glucocerebrosidase (GCase)." (PMID 32509770, 2020). "Whereas homozygous mutations in GBA1 cause Gaucher's disease, heterozygous carriers are of significantly higher risk of PD." (PMID 33106318, 2020). "Gaucher Disease (GD) is an autosomal recessive disease caused by monogenic mutations in the GBA1 gene." (PMID 33287247, 2020). "Homozygous GBA1 loss-of-function mutations lead to the lysosomal storage disorder Gaucher’s disease, characterized by accumulation of GluCer and GluSph within the lysosomes of macrophages." (PMID 33381501, 2020).
Gaucher disease (continued). "Our lab showed in the past that in Gaucher disease (GD), resulting from accumulation of glucosylceramides due to mutations in the GBA1 gene, encoding acid-β-glucocerebrosidase (GCase), the mutant variants are retained in the ER and activate the UPR." (PMID 33036426, 2020). "Gaucher disease (GD) is an autosomal recessive lysosomal storage disorder caused by mutations in the acid β-glucosidase gene (GBA1)." (PMID 32380730, 2020). "The same applies even to patients with Gaucher disease, despite exhibiting significantly attenuated GCase activity as a result of two mutated GBA1 alleles." (PMID 31464647, 2019). "Gaucher disease (GD), a lysosomal storage disorder, results from mutations in GBA1, the gene encoding lysosomal acid β-glucocerebrosidase (GCase)." (PMID 31505865, 2019). "Homozygous mutations in the GBA1 gene cause Gaucher disease (GD), which is the most common lysosomal storage disorder." (PMID 31333408, 2019). "In PD patient carriers of Gaucher disease-linked mutations, haploinsufficiency of GBA1 produces on average a 30–50% reduction of GCase activity, paralleled with increases in glycolipid substrates." (PMID 31331333, 2019). "Gaucher disease (GD) is caused by deficiency of beta-glucocerebrosidase (GCase) due to biallelic variations in the GBA1 gene." (PMID 31077260, 2019). "At least 495 known GBA1 mutations are associated with Gaucher disease, the majority being missense mutations." (PMID 31464647, 2019). "A great deal is known about GBA1, as mutations in GBA1 are causal for the rare autosomal storage disorder Gaucher disease." (PMID 31464647, 2019). "Gaucher disease (GD) is a genetic disease caused by loss of lysosomal glucocerebrosidase (GBA1), responsible for multiorgan malformations and skeletal defects." (PMID 31828085, 2019). "Gaucher disease is an autosomal recessive disorder due to deficient activity of the lysosomal enzyme glucocerebrosidase (GCase) produced by pathogenic mutations in GBA1 gene." (PMID 31150494, 2019). "The association between mutations in GBA1 and the development of parkinsonism was first appreciated in the 1990’s with the identification of rare patients with Gaucher disease who also developed Parkinson disease." (PMID 31464647, 2019). "Gaucher disease (GD) is a rare inherited metabolic disease caused by pathogenic variants in the GBA1 gene." (PMID 30988500, 2019). "Screening for 6–8 specific GBA1 mutations can identify around 95% of mutant alleles in Ashkenazi Jewish patients with Gaucher disease, while the genotypic diversity is far broader in other ethnicities." (PMID 31464647, 2019). "Mutations in GBA1, which encodes glucocerebrosidase (GCase) and causes Gaucher’s disease, are the most common risk factors for PD." (PMID 31133790, 2019). "Gaucher's disease (GD) is characterized by a deficiency of a lysosomal enzyme, glucocerebrosidase which occurs due to mutations in the GBA1 gene on chromosome 1." (PMID 31565589, 2019). "Recently, mutations in the GBA1 gene (encoding glucocerebrosidase), which are responsible for the lysosomal storage disorder Gaucher disease (GD), have been reported to be the strongest risk factor for developing sporadic PD/DLB." (PMID 31333408, 2019). "Disruptive GBA1 mutations are causal to Gaucher disease by leading to insufficient GCase function and resultant GC and GS accumulation." (PMID 30944381, 2019). "Studies of Gaucher’s disease patients have identified almost 300, mostly missense, mutations for GBA1 that negatively impact on GCase stability and function." (PMID 30337601, 2018). "The finding that GBA1 mutations increase the risk of developing PD resulted from observation of a higher incidence of PD in patients with the lysosomal storage disorder, Gaucher’s disease, a recessive disorder also caused by GBA1 mutations." (PMID 30337601, 2018). "Homozygous loss-of-function mutations in GBA1 cause Gaucher’s disease, a lysosomal storage disorder." (PMID 29119326, 2018).
Gaucher disease (continued). "It has been found that patients with Gaucher’s disease have a nearly 20-fold increased risk of developing PD in their life-time, with GBA1 heterozygotes also having an increased risk of PD and an association with earlier onset and more severe forms of PD." (PMID 29481565, 2018). "Homozygous mutations in GBA1 cause a lysosomal storage disorder, Gaucher disease, whereas heterozygous mutations in GBA1 are implicated in PD and DLB." (PMID 29703245, 2018). "In all patients a diagnosis of Gaucher disease was confirmed based upon deficient activity of GBA and/or GBA1 mutation analysis." (PMID 29423829, 2018). "Certain GBA1 mutations are known to be associated with Gaucher Disease (GD) and with Parkinson’s disease (PD)." (PMID 30384423, 2018). "Gaucher disease is an inherited lysosomal storage disorder caused by mutation of the GBA1 (acid-β-glucosidase) gene, which is located on chromosome 1." (PMID 29986415, 2018). "Mutations in the glucocerebrosidase 1 (GBA1) gene are related to both Parkinson disease (PD) and Gaucher disease (GD)." (PMID 28295625, 2017). "Gaucher disease is most frequently caused by mutations in the GBA1 gene which encodes GCase; however, there are rare cases of Gaucher disease caused instead by mutations in the PSAP gene." (PMID 29233882, 2017). "Homozygous mutations in GBA1 cause Gaucher disease, but an increased risk in developing PD has not only been observed for Gaucher disease patients, but already in heterozygous carriers." (PMID 29234271, 2017). "Gaucher disease (GD) is caused by mutations in the GBA1 gene which encodes lysosomal β-glucocerebrosidase (GCase)." (PMID 28166796, 2017). "In fact, concomitant loss of GBA2 activity in a GBA1-mouse model for Gaucher disease rescued the clinical phenotypes although glycosphingolipid levels were increased." (PMID 29234271, 2017). "Classically, mutations in the glucocerebrosidase (GBA1) gene cause the Gaucher’s Disease, a genetic lysosomal disorder." (PMID 28825628, 2017). "Gaucher disease is the most common lysosomal disorder caused by homozygous GBA1 mutations whereas PD is the second most common neurodegenerative disorder after Alzheimer disease." (PMID 28295625, 2017). "It conveys the main hydrolysis of GlcCer in the lysosome and mutations in the GBA1 gene result in a severe lysosomal storage disorder called Gaucher disease." (PMID 29234271, 2017). "Mutations in the glucosidase, beta, acid (GBA1) gene cause Gaucher’s disease, and are the most common genetic risk factor for Parkinson’s disease (PD) and dementia with Lewy bodies (DLB) excluding variants of low penetrance." (PMID 27019408, 2016). "Recent developments have also indicated a probable link between Gaucher disease and Parkinson’s disease where both carriers of a GBA1 mutation and disease sufferers show earlier onset and more severe symptoms of Parkinson’s." (PMID 27228111, 2016). "These include mutations within the GBA1 gene encoding acid beta-glucosidase involved in Gaucher Disease as well as deficiency of lysosomal β-galactosidase in Krabbe disease." (PMID 27228111, 2016). "Pathogenetic mutations in both alleles of GBA1 cause the lysosomal storage disorder Gaucher disease." (PMID 27126635, 2016). "Mutations in the glucosidase, beta, acid (GBA1) gene cause Gaucher’s disease (GD), a lysosomal storage disease that includes neurodegenerative phenotypes." (PMID 27019408, 2016). "Homozygous mutations in the glucocerebrosidase 1 (GBA1) gene have long been known to cause Gaucher disease (GD), the most common lysosomal storage disorder." (PMID 27859541, 2016). "Gaucher disease, the most common lysosomal storage disease, is caused by mutations in the GBA1 gene and is a significant risk factor for Parkinson’s disease; in some forms of Gaucher disease, neuroinflammation is observed." (PMID 27175482, 2016).
Gaucher disease (continued). "Several independent groups have reported increased accumulation of α-synuclein in the brains of mouse models of Gaucher disease with different pathogenetic Gba1 mutations." (PMID 27126635, 2016). "In recent years, research on the pathophysiology of Gaucher disease, the molecular link between Gaucher and Parkinson disease, and novel therapeutics, have accelerated the need for relevant cell models with GBA1 mutations." (PMID 27482815, 2016). "Autosomal recessively inherited glucocerebrosidase 1 (GBA1) mutations cause the lysosomal storage disorder Gaucher's disease (GD)." (PMID 26376862, 2015). "Homozygous mutations in the GBA1 gene are associated with Gaucher’s disease (GD), a lysosomal storage disorder." (PMID 26629917, 2015). "Mutations in glucocerebrosidase (GBA1) cause Gaucher disease and also represent a common risk factor for Parkinson’s disease and Dementia with Lewy bodies." (PMID 25763858, 2015). "Gaucher’s disease is caused by defects in acid β-glucosidase 1 (GBA1) and has been also proposed as an inflammatory disease." (PMID 26312487, 2015). "Gaucher disease (GD) is caused by mutations in the GBA1 gene, which encodes lysosomal β-glucocerebrosidase." (PMID 26045184, 2015). "Viable Gaucher disease mouse models have been created by ‘knocking in’ various point mutations flanked with loxP sequences and inserted in the mouse Gba1 locus encoding GCase including V394L, D409H, D409V, or D409V/null." (PMID 25551612, 2014). "Gaucher disease is of autosomal recessive inheritance and it is caused by mutations in the acid beta-glucosidase 1 (GBA1) gene on chromosome 1q22 in the vast majority of patients." (PMID 25126087, 2014). "Gaucher disease is an autosomal recessively inherited disorder caused by mutations in GBA1 that encodes lysosomal acid β-glucosidase (GCase) (E.C. 3.2.1.45)." (PMID 23520473, 2013). "Gaucher disease results from GBA1 mutations that lead to defective acid β-glucosidase (GCase) mediated cleavage of glucosylceramide (GC) and glucosylsphingosine as well as heterogeneous manifestations in the viscera and CNS." (PMID 23520473, 2013). "Gaucher disease (GD) is the most common lysosomal storage disease and arises from mutations in the gene encoding the lysosomal glucocerebrosidase (GBA1; EC 3.2.145, MIM# 606463)." (PMID 24070122, 2013). "To determine the frequency of mutations responsible for Gaucher's disease, we systematically sequenced the GBA1 gene as part of a molecular characterization of 73 adult patients in the United Kingdom." (PMID 22658918, 2012). "The identification of the glucocerebrosidase locus (GBA1) as a strong genetic determinant of Parkinson's disease (PD), renders it difficult to counsel patients with Gaucher's disease (GD) and their relatives as to their lifetime risk of this disorder." (PMID 22658918, 2012). "Gaucher disease (GD) is a lysosomal storage disorder caused by biallelic GBA1 variants." (PMID 41675236, 2026). "Sap C deficiency resembles another rare autosomal recessive disorder, Gaucher disease (GD), in which pathogenic variants in the GBA1 gene result in GCase deficiency and accumulation of glucosylceramide within the lysosomal compartment of the mononuclear phagocyte system." (PMID 41812503, 2026). "This hypothesis would be in line with our finding of two different heterozygous ClinVar LP/P GVs in GBA1 in three glioblastoma patients, and an increased risk of hematological malignancies and solid tumors in patients with Gaucher disease." (PMID 41546701, 2026). "In neuropathic forms of Gaucher disease—caused by mutations in the GBA1 gene leading to glucocerebrosidase deficiency—the accumulation of undegraded substrates in lysosomes results in widespread cellular dysfunction, including neuroinflammation and neurodegeneration." (PMID 40423231, 2025).
Gaucher disease (continued). "Gaucher disease (GD), caused by biallelic pathogenic variants in GBA1, has evolved from being understood as a macrophage-restricted lysosomal disorder to a multisystem condition involving neuroinflammation, immune dysregulation, and cell-type-specific lipid toxicity." (PMID 41465340, 2025). "Mutations in GBA1 were the most common finding: 29 pathogenic variants were found in 28/218 patients (12.8% of the cohort, 62% of positive diagnosis), with biallelic mutations in one patient consistent with a diagnosis of Gaucher disease associated with PD." (PMID 39034353, 2025). "Deficiency of GCase activity (in the context of biallelic GBA1 mutations) causes the autosomal-recessive lysosomal storage disorder Gaucher disease (GD), typified by hepatosplenomegaly, bone involvement, cytopenias, and in the neuronopathic forms (types 2 and 3), severe neurodegeneration." (PMID 41465169, 2025). "Interestingly, different variants in the GBA1 gene (associated with Gaucher disease) can act as genetic risk factors for parkinsonism or even cause a monogenic form of Parkinson disease with reduced penetrance (PARK-GBA1)." (PMID 41517394, 2025). "Comparative studies of dopaminergic (DA) neurons differentiated from iPSCs derived from siblings with Gaucher disease discordant for parkinsonism provides a valuable avenue to explore genetic modifiers contributing to GBA1-associated parkinsonism in disease-relevant cells." (PMID 38529501, 2024). "Gaucher Disease (GD) is an inherited metabolic disorder caused by mutations in the GBA1 gene." (PMID 38757200, 2024). "Since we have recently reported siblings with MSA-C and PD sharing a GBA1 variant pathogenic for Gaucher disease, the observation may suggest a role of GBA1 variants as a common genetic basis underlying PD and MSA." (PMID 39020124, 2024). "Biallelic GBA1 mutations result in the rare lysosomal storage disease Gaucher disease (GD)." (PMID 38529501, 2024). "GBA1 mutations frequently give rise to lysosomal storage disorders like Gaucher disease (GD)." (PMID 38396963, 2024). "Notably, among the participants, 14 carried two GBA1 variants, with 9 having homozygous variants, while 6 of these cases involved Gaucher disease-associated variants, including N370S/N409S." (PMID 39766872, 2024). "Gaucher disease (GD) is a metabolic disorder caused by mutations in the GBA1, located on 1q22." (PMID 39850539, 2024). "Gaucher disease (GD) is a rare genetic metabolic disorder characterized by a dysfunction of the lysosomal glycoside hydrolase glucocerebrosidase (GCase) due to mutations in the gene GBA1, leading to the cellular accumulation of glucosylceramide (GlcCer)." (PMID 38257371, 2024). "Starting from the observation that family members of patients with Gaucher disease have a considerably high prevalence of Parkinson disease (PD), numerous studies have consistently shown that deleterious variants of GBA1 are strong risk factors for the development of PD." (PMID 39020124, 2024). "•Gaucher disease (GD) is a metabolic disorder caused by mutations in the GBA1 gene." (PMID 39850539, 2024). "The critical role played by GCase in preventing substrate accumulation, avoiding lipid dysmetabolism and preserving cellular structures and functions is indicated by the deleterious consequences of homozygous GBA1 mutations that cause Gaucher disease, the most common lysosomal storage disease." (PMID 39663354, 2024). "Hence, we also examined BMP concentrations in the urine from Gaucher disease-associated severe GBA1 variant carriers." (PMID 36854767, 2023). "In addition, Gaucher disease (GD) patients, who carry a homozygous mutation in the GBA1 gene, are known to experience metabolic disturbances." (PMID 38110400, 2023). "GBA1 mutations cause Gaucher’s disease and are the strongest risk factor for Parkinson’s disease." (PMID 37024507, 2023). "Mutations in GBA1 cause Gaucher disease (GD) with varying disease severity." (PMID 37045813, 2023).